PLD6 (phospholipase D family member 6)
Description:
Presents phospholipase and nuclease activities, depending on the different physiological conditions. Interaction with Mitoguardin (MIGA1 or MIGA2) affects the dimer conformation, facilitating the lipase activity over the nuclease activity. Plays a key role in mitochondrial fusion and fission via its phospholipase activity. In its phospholipase role, it uses the mitochondrial lipid cardiolipin as substrate to generate phosphatidate (PA or 1,2-diacyl-sn-glycero-3-phosphate), a second messenger signaling lipid. Production of PA facilitates Mitofusin-mediated fusion, whereas the cleavage of PA by the Lipin family of phosphatases produces diacylgycerol (DAG) which promotes mitochondrial fission. Both Lipin and DAG regulate mitochondrial dynamics and membrane fusion/fission, important processes for adapting mitochondrial metabolism to changes in cell physiology. Mitochondrial fusion enables cells to cope with the increased nucleotide demand during DNA synthesis. Mitochondrial function and dynamics are closely associated with biological processes such as cell growth, proliferation, and differentiation. Mediator of MYC activity, promotes mitochondrial fusion and activates AMPK which in turn inhibits YAP/TAZ, thereby inducing cell growth and proliferation. The endonuclease activity plays a critical role in PIWI-interacting RNA (piRNA) biogenesis during spermatogenesis. Implicated in spermatogenesis and sperm fertility in testicular germ cells, its single strand-specific nuclease activity is critical for the biogenesis/maturation of PIWI-interacting RNA (piRNA). MOV10L1 selectively binds to piRNA precursors and funnels them to the endonuclease that catalyzes the first cleavage step of piRNA processing to generate piRNA intermediate fragments that are subsequently loaded to Piwi proteins. Cleaves either DNA or RNA substrates with similar affinity, producing a 5' phosphate end, in this way it participates in the processing of primary piRNA transcripts. piRNAs provide essential protection against the activity of mobile genetic elements. piRNA-mediated transposon silencing is thus critical for maintaining genome stability, in particular in germline cells when transposons are mobilized as a consequence of wide-spread genomic demethylation (By similarity). PA may act as signaling molecule in the recognition/transport of the precursor RNAs of primary piRNAs. Interacts with tesmin in testes, suggesting a role in spermatogenesis via association with its interacting partner (By similarity).
Synonyms: Zuc
Tractability: Antibody: UniProt predicts a signal peptide or a membrane-spanning region. PROTAC: ubiquitination databases record sites on it.
Gene: Protein-coding gene on chromosome 17 (17,200,995 to 17,206,333, reverse strand). Ensembl gene ENSG00000179598.
Subcellular location: Mitochondrion outer membrane; Golgi apparatus
Pathways (Reactome):
Metabolism: Synthesis of PA; Synthesis of PG
Gene expression (Transcription): PIWI-interacting RNA (piRNA) biogenesis
Gene Ontology:
Molecular function: cardiolipin hydrolase activity; protein binding; protein homodimerization activity; RNA endonuclease activity producing 5'-phosphomonoesters, hydrolytic mechanism; catalytic activity; identical protein binding; phospholipase D activity
Biological process: mitochondrial fusion; phospholipid biosynthetic process; positive regulation of mitochondrial fusion; meiotic cell cycle; P granule organization; piRNA processing; spermatid development
Cellular component: mitochondrial outer membrane; mitochondrion; Golgi apparatus
Genetic constraint (gnomAD): Loss-of-function variants: 10 observed, 6.9 expected, observed/expected ratio (o/e) 1.45, 90% interval 0.86 to 1.92. That is too few expected variants to judge how well the gene tolerates losing a copy. Missense variants: 334 observed, 282.36 expected, observed/expected ratio (o/e) 1.18, 90% interval 1.08 to 1.29. Synonymous variants: 152 observed, 118.65 expected, observed/expected ratio (o/e) 1.28, 90% interval 1.12 to 1.47.
Homologues: Orthologues: chimpanzee PLD6 (99% identical), macaque PLD6 (83% identical), dog PLD6 (75% identical), pig PLD6 (73% identical), mouse Pld6 (73% identical), guinea pig PLD6 (70% identical), rat Pld6 (62% identical), tropical clawed frog pld6 (50% identical), zebrafish pld6 (42% identical), Drosophila melanogaster zuc (25% identical).
Diseases named in the same sentence as PLD6 in open-access papers:
PLD6 is named in the same sentence as 16 diseases in open-access papers, as found by Europe PMC text mining. Sharing a sentence is not in itself a finding about the gene and the disease. The quoted sentences say what the papers report.
breast carcinoma (3 papers, 2017 to 2024). "A recent study done in normal mammary and breast cancer cells showed that Myc promotes mitochondrial fusion by promoting phospholipase D family member 6 (PLD6) activity and that this fusion facilitates mitochondrial bioenergetics." (PMID 28513539, 2017). "The molecular action for PIWIL3 and PLD6 in low grade OC could be involvement in growth regulation such as in glioma and mediating downstream pathways for proto-oncogene, MYC, as seen in breast cancer, respectively." (PMID 33374923, 2020).
Infertility (3 papers, 2021 to 2023). "In pld6 mutants, GSPCs fail to differentiate and undergo apoptosis, leading to masculinization and infertility." (PMID 36257818, 2022). "In addition, the male PLD6−/− mice showed dramatically decreased piRNAs, damaged structure of the nucleoid body, blocked spermatogenesis at the pachytene stage, and infertility." (PMID 37569546, 2023).
male infertility (2 papers, 2021 to 2022). The inability of the male to effect fertilization of an ovum after a specified period of unprotected intercourse. "To confirm that male infertility defect was induced by genetic loss of pld6, we recovered the pld6 expression by transgenic technology." (PMID 36257818, 2022). "Knockdown of pld6 reduced the PGC number, but did not induce any other developmental defects at early embryonic stage, whereas zygotic knockout of pld6 resulted in female‐to‐male sex reversal and male infertility." (PMID 36257818, 2022).
ankylosing spondylitis (1 paper, 2023). An autoimmune chronic inflammatory disorder characterized by inflammation in the vertebral joints of the spine and sacroiliac joints. "Moreover, though PLD6 was not detectable in RA, it is reported that carrying HLA-B*27 was associated with robust hypomethylation of PLD6 in ankylosing spondylitis patients." (PMID 37325646, 2023).
Azoospermia (1 paper, 2024). Absence of any measurable level of sperm,whereby spermatozoa cannot be observed even after centrifugation of the semen pellet. "in M2173, were identified in PLD6 in two men with azoospermia due to SCO." (PMID 39122675, 2024).
colorectal cancer (1 paper, 2025). A primary or metastatic malignant neoplasm that affects the colon or rectum. "This study explores the role of a protein called phospholipase D6 (PLD6) in colorectal cancer (CRC)." (PMID 40259095, 2025).
diabetic retinopathy (1 paper, 2024). "Previous GWAS studies have also found associations between variants in PLD6 and both BMI and diabetic retinopathy." (PMID 38574408, 2024).
stomach cancers (1 paper, 2025). "The PLD6 expression was significantly elevated in various cancer tissues, including colorectal, breast, renal, lung, liver, prostate and stomach cancers." (PMID 40259095, 2025).
Type 1 Diabetes (1 paper, 2024). "We found GWAS links between 7 T2D-DMP genes and T2D or related phenotypes, including SPRED2 (T2D), ITPR1 and PLD6 (Diabetic complications), SLC16A3 (BMI), TCF7 (Type 1 Diabetes), RGL3 (blood pressure) and TNIP1 (autoimmune traits)." (PMID 38574408, 2024).
cancer (3 papers, 2020 to 2025). A tumor composed of atypical neoplastic, often pleomorphic cells that invade other tissues. "Consequently, PLD6 ablation reduces cancer stem cell-associated gene expression downstream of Wnt/β-catenin signaling, suppressing stem-like traits and chemoresistance to 5-fluorouracil." (PMID 40259095, 2025). "They found that PLD6 promotes cancer cell growth, movement and survival by affecting mitochondrial metabolism and a signaling pathway called Wnt/β-catenin, which is important for cell growth and development." (PMID 40259095, 2025). "The proportion of PLD6-positive samples increased significantly with advancing cancer stage (p < 0.001)." (PMID 40259095, 2025). "Targeting PLD6 in both subcutaneous and orthotopic cancer mouse models attenuated tumorigenesis possibly by suppressing Wnt/β-catenin signaling, thereby sensitizing CRC cells to 5-FU-induced apoptosis." (PMID 40259095, 2025). "To explore the role of PLD6 in cancer, we first analyzed its differential expression across various cancer types using TIMER2.0." (PMID 40259095, 2025). "Considering that PLD6 is essential for mitochondrial fusion, we hypothesized that it may significantly regulate mitochondrial function and cancer metabolism." (PMID 40259095, 2025). "PLD6 is known to be involved in mitochondrial function, but its role in cancer was unclear." (PMID 40259095, 2025). "However, the role of PLD6 in cancer has not yet been elucidated." (PMID 40259095, 2025).
tumor (2 papers, 2025). "PLD6-deficient cells showed significantly lower tumor size, weight and volume compared with those of control cells." (PMID 40259095, 2025). "To investigate whether PLD6 regulates CRC tumorigenesis in vivo, we used an orthotopic tumor model in which PLD6-deficient MC38 cells were injected into the cecal submucosa of mice." (PMID 40259095, 2025). "Consistent with the orthotopic model, PLD6-KO cells showed significantly attenuated tumor development in the subcutaneous model." (PMID 40259095, 2025). "The tumor tissues derived from mice injected with PLD6-KO cells exhibited reduced proliferation and increased apoptosis compared with those from control cell-injected mice, as indicated by IHC staining for Ki67 and active caspase-3." (PMID 40259095, 2025). "In this study, we investigate the functional role of mitochondrial metabolism in CRC tumor growth and initiation, focusing on the potential involvement of PLD6 in CRC progression." (PMID 40259095, 2025). "We identified PLD6-mediated mitochondrial metabolism as a key regulator of Wnt signaling and tumor progression in CRC." (PMID 40259095, 2025). "PLD6 KO suppressed CRC cell proliferation and increased apoptosis in tumor tissues, as indicated by IHC analysis." (PMID 40259095, 2025). "Furthermore, PLD6 depletion attenuates CRC tumorigenesis in both subcutaneous and orthotopic tumor models." (PMID 40259095, 2025). "The study suggests that targeting PLD6 could be a potential strategy for treating CRC, as it may help reduce tumor growth and improve the effectiveness of chemotherapy." (PMID 40259095, 2025).
PLD6 also shares sentences with these, for which no sentence is quoted: asthenozoospermia (1 paper); colon cancer (1); diabetes (1); glioma (1); mitochondrial disease (1).